S100B (S100 calcium binding protein B)
Diseases named in the same sentence as S100B in open-access papers (continued):
Sharing a sentence is not in itself a finding about the gene and the disease.
dementia (29 papers, 2009 to 2025). Loss of intellectual abilities interfering with an individual's social and occupational functions. "Lambert (2007) found that the S100B polymorphism rs2300403 was correlated with low cognitive performance and dementia in elderly people, thereby underlining the importance of S100B in genetic susceptibility to AD." (PMID 33982673, 2021). "High and increasing concentrations of serum S100β at this age is identified here as a potentially meaningful marker of poorer brain white matter health and, with further testing, risk of future dementia." (PMID 29933100, 2018). "In addition, the rs2300403 single nucleotide polymorphism (SNP) in the S100B gene is associated with low cognitive performance, dementia and AD." (PMID 21080947, 2010). "The relationships among serum oxytocin, S100B, and cognitive function (Mini‐Mental State Examination, Frontal Assessment Battery, and Clinical Dementia Rating) were analyzed using correlation and multiple regression analyses." (PMID 40487975, 2025). "The average increase in the concentration of these proteins is about 1% per year, with high levels of NSE or S100B appearing more frequently in older individuals with dementia." (PMID 39519343, 2024). "NfL and tau are proteins expressed in axons, NSE in neurons and S100B in glial cells and are used as biomarkers for neurological injury in other diseases such as dementia, traumatic brain injury and hypoxic brain injury." (PMID 35269411, 2022). "It is demonstrated that sera of AD patients with moderate and severe dementia have a 60- and 37-fold increase in S100B, respectively." (PMID 31156365, 2019). "The autoimmune responses to Aβ oligomers reflected mild to moderate phases of AD dementia, while those to S100B protein closely matched moderate to severe dementia." (PMID 21541339, 2011). "Serum/CSF S100B levels inversely correlate with cognitive function, i.e patients with lower S100B levels exhibit lower Clinical Dementia Rating scores and higher Mini-Mental State Examination scores." (PMID 21080947, 2010). "Studies implicating S100β as a candidate marker for dementia are often performed in cerebrospinal fluid, which may provide a closer reflection of brain pathology and comparisons between blood and CSF S100β levels may therefore yield differing conclusions." (PMID 35028426, 2021). "In addition, CSF S100β levels were higher in individuals with moderate to severe dementia who succumbed to their disease more rapidly than those who deteriorated more slowly with the same dementia stage." (PMID 30678707, 2019). "This hypothesis is supported by the inverse correlation of serum/CSF S100B levels and direct correlation of the rs2300403 SNP in the S100B gene with low cognitive performance, dementia and AD." (PMID 21080947, 2010). "We determined insulin resistance using the homeostatic model assessment (HOMA-IR), which is interchangeable with T3D, and dementia risk markers (cognitive executive functioning (cognitiveexe-func); telomere length; waist circumference (WC), neuronal glia injury; neuron-specific enolase/NSE, S100B)." (PMID 33670473, 2021). "No relevant associations were found between any of the CERAD-Plus subtests and the CSF parameters S100B, NSE, and tTau in our patients with initial or clinically manifest dementia." (PMID 39941381, 2025). "Presumed cognitive dysfunction blood biomarkers (SAA, Hcy, S100B, BDNF) will be used as predictive factors for the development of MCI or dementia in the study groups." (PMID 37824197, 2023). "We compared different CSF biomarkers reflecting neurodegeneration (NFL) and inflammation (YKL-40, S100B and GFAP) in relation to core CSF AD markers and cognitive functions in a cohort of subjects at the pre- and early symptomatic dementia stages." (PMID 32753068, 2020). "Toward that goal, this study aimed to test the relationship between plasma S100B levels and both memory and executive function in older adults without dementia." (PMID 39907937, 2025).
dementia (continued). "We investigated the relationships between plasma S100B levels, multiple MRI measures associated with cerebrovascular disease (CVD), and cognition in a community-based sample of older adults without dementia." (PMID 39907937, 2025). "The first aim of this study was to assess the ability of glial (YKL-40, S100B, GFAP) and neurodegeneration (NFL) markers in CSF to discriminate between different CSF profiles (AD and non-AD) among subjects at the symptomatic pre- and early stages of dementia." (PMID 32753068, 2020). "CSF levels of S100β have previously been shown to be significantly higher in patients with moderate to severe HAD (formerly called AIDS dementia complex stages 2–3) than in patients with mild (stage 1) or no dementia." (PMID 30678707, 2019). "Our findings show that the three CSF parameters S100B, NSE, and tTau, do not allow for firm predictions of neuropsychological performance in dementia patients." (PMID 39941381, 2025). "There are also reports suggesting a positive correlation between CSF S100B levels and MMSE, and a negative correlation with severity of dementia by CDR scale while in others CSF S100B levels did not correlate with impaired cognitive status evaluated by MMSE." (PMID 20105309, 2010).
Encephalopathy (29 papers, 2010 to 2026). Encephalopathy is a term that means brain disease, damage, or malfunction. "Cord blood S100b was positively associated with both severity of encephalopathy and the risk of neurodevelopmental sequelae." (PMID 30086156, 2018). "Severe hypotension (OR: 2.56 (1.18, 4.75), p = 0.022), longer sedation duration (OR: 1.09 (1.02, 1.18), p = 0.017), ICU-acquired infections (OR: 1.61(0.73, 3.54), p = 0.021), and elevated S100B (OR: 1.72 (0.66, 3.65), p = 0.03) were associated with encephalopathy." (PMID 41788477, 2026). "Accordingly, in addition to S100B, the functional prognosis in our cohort was impacted by the occurrence of MV and the presence of severe encephalopathy." (PMID 39779630, 2025). "Key predictors of worsening mRS included mechanical ventilation (OR = 9.56, 95% CI = 1.67–54.75; p = 0.011), severe encephalopathy (OR = 5.10, 95% CI = 1.58–16.19; p = 0.006), and elevated S100B levels (OR = 2.62, 95% CI = 1.10–6.46; p = 0.037)." (PMID 39779630, 2025). "In accordance with our study, in most previous studies S100B levels in preterm controls were stable over time, whereas levels in preterms with encephalopathy were decreasing over time." (PMID 37292373, 2023). "Preterms with encephalopathy presented higher S100B levels than preterm controls on day 1, mainly the ones with severe IVH (grade III/IV)." (PMID 37292373, 2023). "An increase of S100B in prematures with encephalopathy was observed on the first day of life compared to preterms without detectable brain damage, a constant observation in previous studies." (PMID 37292373, 2023). "S100B levels more closely reflected severe encephalopathy and type of brain lesions than NSE and GCS." (PMID 23905041, 2012). "Moreover, S100B seems to be a promising biomarker for the long-term follow-up of PE encephalopathy, either independently or in combination with other brain injury biomarkers (such as NSE or NfL) and/or imaging techniques." (PMID 40563479, 2025). "Furthermore, the level of the brain injury biomarker S100β was significantly higher in the encephalopathy group (2.03 ± 0.18 μg/L vs. 2.15 ± 0.29 μg/L, P = .020)." (PMID 41189156, 2025). "In addition to increased expression of S100B in activated astrocytes in neurological conditions, systemic diseases such as mild to severe liver disease is characterized by dramatic increases in astrocyte-derived S100B expression, encephalopathy, and cognitive decline." (PMID 23866266, 2013). "In infants with hypoxic-ischemic encephalopathy (HIE), S100B levels are higher in moderate-to-severe compared with mild HIE and correlate with the severity of encephalopathy, extent of MRI injury, and adverse outcomes including cerebral palsy and death." (PMID 40963746, 2025). "Serum S100B levels were increased only in the subgroup of neonates with severe encephalopathy, while NSE levels were significantly correlated with the grading of encephalopathy, providing excellent prognostic ability, as shown in detail earlier." (PMID 40149963, 2025). "Regarding brain damage, BAM15 attenuated encephalopathy score (SHIRPA) and several injury parameters, including brain cytokine (TNF-α), apoptosis (activated caspase 3), blood–brain barrier defect (Evan’s blue dye assay), s100β, and miR370-3p." (PMID 35628259, 2022). "The amino-terminal propeptide of the C-type natriuretic peptide (NT-proCNP) was compared as a biomarker of septic encephalopathy with neuron-specific enolase (NSE) and S100B protein in 12 patients diagnosed septic encephalopathy and 9 non-septic control patients without encephalopathy." (PMID 37744876, 2023). "In a meta-analysis of 28 studies with 1,401 serum samples from patients with septic encephalopathy and 1,591 serum samples from septic patients without encephalopathy, patients with septic encephalopathy had higher serum S100B concentrations than septic control patients." (PMID 37744876, 2023).
Encephalopathy (continued). "We consider that the mechanism of encephalopathy caused by Klebsiella pneumonia and Pseudomonas aeruginosa may be related to leaky BBB, however, validation of S100B protein in patients with SAE was lacking in this study, further validation of the mechanism will be required in the future." (PMID 39802659, 2024).
Parkinson disease (29 papers, 2013 to 2025). A progressive degenerative disorder of the central nervous system characterized by loss of dopamine producing neurons in the substantia nigra and the presence of Lewy bodies in the substantia nigra and locus coeruleus. "Similar to S100B, in proteinopathies like Alzheimer’s and Parkinson’s disease, CLU has been found to associate with protein aggregates and might be involved in their clearance." (PMID 36243678, 2022). "Preclinical and clinical evidence has demonstrated that astroglial-derived S100B protein is a key element in neuroinflammation underlying the pathogenesis of Parkinson’s disease (PD), in so much as that S100B inhibitors have been proposed as promising candidates for PD targeted therapy." (PMID 30669702, 2019). "For example, S100β levels in serum and cerebrospinal fluid has been shown to correlate with disease severity in Parkinson’s disease." (PMID 38713518, 2024). "It is noteworthy that S100B has been suggested to be involved in the pathogenesis of some neurological diseases, such as Parkinson’s disease and multiple sclerosis, making it a possible treatment target." (PMID 37474905, 2023). "Both, S100B and CLU, are associated with many neurological disorders such as Alzheimer’s disease and Parkinson’s disease in humans that involve hypoxia and oxidative stress." (PMID 36243678, 2022). "S100β, a Ca++-binding protein, has been reported to develop features of Parkinson’s disease (PD), such as the impairment of motor coordination and the expression of some molecular parameters, including the dopamine D2 receptor." (PMID 34572572, 2021). "Knockout of S100β in mice partially rescued neuronal death in an MPTP Parkinson’s model." (PMID 40843691, 2025). "Brain tissue samples from patients with Parkinson’s disease show increased S100β protein levels." (PMID 40843691, 2025). "Nevertheless, in proteinopathies like Alzheimer’s and Parkinson’s disease, S100B might also be involved in clearance of detrimental protein aggregates." (PMID 36243678, 2022). "S100β was found to be expressed most in thalamus astrocytes, a subtype of cells that participate in the cleaning of DAergic debris produced by the degeneration of DAergic terminals in Parkinson's disease by facilitating the presence of lysosomes and the formation of autophagosomes." (PMID 31341912, 2019).
Cerebral ischemia (27 papers, 2010 to 2025). Restriction of arterial blood supply to the brain associated with insufficient oxygenation to support the metabolic requirements of the tissue. "S100B expressed during cerebral ischemia, is capable of causing neuronal damage by inducing overexpression of nitric oxide synthase and subsequent release of nitric oxide, activation of NF-κB in response to inflammation, and activation of microglia." (PMID 39001884, 2024). "S100B elevation is frequently associated with minor brain ischemia, which is relatively frequent in elderly patients undergoing AVR and recognized as biomarker of poor prognosis in these patients." (PMID 32741773, 2020). "Further quantification using Pearson's coefficient confirmed that protein lactylation predominantly occurs in neurons following cerebral ischemia, with a slight increase noted in co‐localization with the astrocytic marker S100β." (PMID 40271828, 2025). "In a cerebral ischemia mouse model, injection of S100β significantly increased infarct size, percentage of TUNEL-positive neurons, and M1 microglial markers." (PMID 40843691, 2025). "Following a single tail vein injection of LGU (2.16 mg/kg), there was a notable reduction in the S100B content in the serum of rats with cerebral ischemia." (PMID 38927572, 2024). "Although S100β, at low concentrations, displays a neuroprotective effect, the release of large amounts of S100β by astrocytes in prolonged cerebral ischemia has a neurotoxic effect, a feature possibly observed in patients with severe hypothermia." (PMID 38611652, 2024). "Prior work identified high levels of S100β, a glial-derived protein marker of cerebral ischemia, in HLHS patients." (PMID 38143535, 2023). "In the brain ischemia cellular microenvironment, S100b is released as a molecule that triggers an inflammatory response." (PMID 33192985, 2020). "The patients experiencing vasospasm leading to cerebral ischemia had higher S100B levels from the beginning and enhanced incidence of poor outcome." (PMID 30011792, 2018). "As detailed below, we found support that pharmacological strategies aimed at inhibiting S100B abundance would, in principle, be beneficial to mitigate cerebral ischemia." (PMID 20862385, 2010). "In this paper, we have considered beneficial physiological functions and detrimental roles of the astrocyte-derived protein S100B in cerebral ischemia and in AD." (PMID 20862385, 2010). "During cerebral ischemia, S100B was found to be abundantly expressed in microglia." (PMID 39001884, 2024). "Overexpression of S100B which is expressed in microglia could aggravate cerebral ischemia through activating NF-κB expression and inhibiting M2 stimuli expression to promote microglia M1 polarization." (PMID 32908485, 2020). "It is known that cerebral ischemia increases serum levels of S-100B." (PMID 23227020, 2012). "However, the function of S100b in OLGs needs to be further explored after cerebral ischemia." (PMID 38180614, 2024). "Therefore, we propose that EA at acupoints exerts its neuroprotective effects against delayed infarct expansion and neurological deficits, at least partly, through the downregulation of S100B expression in the periinfarct area during the subacute phase of cerebral ischemia." (PMID 24626220, 2014). "The S100B/RAGE-induced upregulation of NO and TNF-α synthesis in neurons and glial cells causes oxidative stress and neuronal apoptosis, leading to cerebral infarct expansion, which plays a pivotal pathological role during the subacute phase of cerebral ischemia." (PMID 24626220, 2014). "In this patient cerebral ischemia and chronic SDH were the only detectable, as found by radiological examinations, source of S-100B from CNS." (PMID 23227020, 2012).
Cerebral ischemia (continued). "Cases with electronically available data on NSE and S100B serum levels, new intracranial pathologies (intracerebral hemorrhage [ICH], subarachnoid hemorrhage [SAH], cerebral ischemia, hypoxic-ischemic encephalopathy [HIE]), and survival during or after V-V ECMO were screened." (PMID 39695311, 2024). "Considering our and previous findings, we suggest that S100B/RAGE upregulates iNOS and TNF-α expression through p38 MAP kinase-induced NF-κB activation in the ischemic cortical penumbra during the subacute phase of mild cerebral ischemia." (PMID 24626220, 2014).
Anxiety (26 papers, 2010 to 2025). Intense feelings of nervousness, tension, or panic often arise in response to interpersonal stresses. "Mice whose gene encoding S100B was inactivated showed increased spatial memory and memorization under the influence of anxiety and increased long-term synaptic enhancement in the CA1 sector of the hippocampus." (PMID 34073816, 2021). "The mice with an inactivated gene encoding S100B showed increased spatial memory and anxiety storage, and increased long-term synaptic enhancement in the hippocampal CA1 sector." (PMID 32326589, 2020). "Importantly, the altered prefrontal-cingulate-amygdala subnetwork, nodal efficiency of the right amygdala, IL-8, IL-17, and s-100β levels were risk factors for the diagnosis of UD, whereas anxiety symptoms tended to closely correlate with BD." (PMID 40224600, 2023). "It was found that compared with Sham group, combined exposure to EMP and RF induced anxiety-like behavior, increased the level of serum S100B and decreased the level of serum 5-HT." (PMID 37006533, 2023). "Another study found that S100B-positive cells and anxiety levels were markedly increased after treatment." (PMID 35815053, 2022). "Meryem reported decreased S100B levels in the hippocampus and prefrontal cortex in anxious diabetic rats, which were revised by anti-anxiety therapy." (PMID 35815053, 2022). "For example, Xiao Chai Hu decoction may alleviate patients' anxiety symptoms by decreasing the levels of factors related to brain neurological function such as S100B, MBP, NSE and IGF-1." (PMID 38027586, 2023). "S100B could represent a protective factor in the acute phase of anxiety, yet with the development of the disease, S100B decrease may be due to decompensation." (PMID 37763190, 2023). "Similar results were found between S100B levels and anxiety and depressive-like behaviors." (PMID 35200304, 2022). "S100B may be a protective factor in the acute stage of anxiety when individuals face stress." (PMID 35815053, 2022). "However, unlike Shank KO mice or prenatal zinc-deficient mice, S100B exposed mice do not show increased anxiety behavior." (PMID 34741005, 2021). "Information was obtained from 19 patients using the State-Trait Anxiety Inventory (STAI) and analysis of BDNF, NSE and S100B serum levels." (PMID 38055476, 2023). "Several lines of research highlight the need to explore the relationship between BDNF and anxiety peripheral levels as well as the importance of other biomarkers such as NSE and S100B." (PMID 38055476, 2023). "Regarding antioxidant properties of melatonin, Ergenc and co-workers examined melatonin effects on S100B, AGE receptor (AGER), and AGE levels, oxidative stress, and anxiety and depressive like-behaviors in streptozotocin-mediated diabetic rats." (PMID 32280378, 2020). "The relationship of S100B with HAMD, Hamilton Anxiety Scale (HAMA) score, and WCST results was evaluated subsequently." (PMID 30278520, 2018). "The absence of increased anxiety also hints at the presence of further modifying factors in S100B exposed mice or Shank2 and Shank3 KO mice that modulate the phenotype, such as extracerebral factors like gastrointestinal abnormalities that, for example, have been reported in Shank3 KO mouse models." (PMID 34741005, 2021). "However, across all children the CPRS ratings of anxiety (not inattention or opposition) showed a weak bivariate tendency to relate to S100B levels (n = 56, r = +0.23, p < 0.09)." (PMID 20509936, 2010). "However, S100B levels were lower in those children expressing higher levels of non-externalizing symptoms (e.g. mood, anxiety)." (PMID 20509936, 2010).